EEF1AKMT3 (EEF1A lysine methyltransferase 3)
Description:
Protein-lysine methyltransferase that selectively mono-, di- and trimethylates 'Lys-165' of the translation elongation factors EEF1A1 and EEF1A2 in an aminoacyl-tRNA and GTP-dependent manner. EEF1A1 methylation by EEF1AKMT3 is dynamic as well as inducible by stress conditions, such as ER-stress, and plays a regulatory role on mRNA translation.
Synonyms: FAM119B; METTL21B; DKFZP586D0919
Tractability: Small molecule: a structure with a bound ligand is known.
Gene: Protein-coding gene on chromosome 12 (57,771,492 to 57,782,541, forward strand). Ensembl gene ENSG00000123427.
Subcellular location: Cytoplasm; Cytoplasm, cytoskeleton, microtubule organizing center, centrosome
Subcellular location (Human Protein Atlas): Centrosome; Mitotic chromosome; Nucleoplasm
Gene Ontology:
Molecular function: heat shock protein binding; methyltransferase activity; protein binding; protein-lysine N-methyltransferase activity
Cellular component: centrosome; cytoplasm; protein-containing complex; cytosol
Genetic constraint (gnomAD): Loss-of-function variants: 17 observed, 18.95 expected, observed/expected ratio (o/e) 0.9, 90% interval 0.61 to 1.35. The upper end of that interval is the gene's LOEUF score, 1.35, which puts it in group 5 of 6, group 1 being the genes least tolerant of losing a copy. Missense variants: 244 observed, 304.01 expected, observed/expected ratio (o/e) 0.8, 90% interval 0.72 to 0.89. Synonymous variants: 116 observed, 136.98 expected, observed/expected ratio (o/e) 0.85, 90% interval 0.73 to 0.99.
Homologues: Orthologues: chimpanzee EEF1AKMT3 (100% identical), pig EEF1AKMT3 (93% identical), guinea pig EEF1AKMT3 (91% identical), rat Eef1akmt3 (87% identical), mouse Eef1akmt3 (85% identical), tropical clawed frog eef1akmt3 (58% identical). Paralogues in human: METTL21A (40% identical), METTL21EP (34% identical), VCPKMT (30% identical), METTL21C (29% identical), METTL23 (19% identical).
Diseases named in the same sentence as EEF1AKMT3 in open-access papers:
EEF1AKMT3 is named in the same sentence as 10 diseases in open-access papers, as found by Europe PMC text mining. Sharing a sentence is not in itself a finding about the gene and the disease. The quoted sentences say what the papers report.
gastric cancer (2 papers, 2023 to 2024). A primary or metastatic malignant neoplasm involving the stomach. "For example, low expression of EEF1AKMT3, which has a tumor suppressive function, correlates with poor prognosis of gastric cancer." (PMID 39309445, 2024). "EEF1AKMT3 has been identified as a tumor suppressor in gastric cancer." (PMID 38036730, 2023). "The expression of EEF1AKMT3 is significantly decreased in gastric cancer tissues vs. normal tissues in patients, and a low level of EEF1AKMT3 expression has been linked to a poor prognosis." (PMID 38036730, 2023).
tumor (5 papers, 2012 to 2024). "Several PKMTs, including MLL3, PRDM2/RIZ, PRDM5, SMYD4, SUV4-20H2, and EEF1AKMT3, have been reported to exhibit tumor suppressor activities." (PMID 38036730, 2023). "Mechanistically, the methylation of MAP2K7 by EEF1AKMT3 was shown to impede tumor activity by promoting the stabilization of TP53188." (PMID 38036730, 2023). "EEF1AKMT3 mediates the methylation of lysine residue 296 of the MAP2K7 protein, which has been implicated in tumor suppression." (PMID 38036730, 2023). "EEF1AKMT3, BHLHE40, and HMGB2 were activated in 11 tumor-related clusters of P128T." (PMID 37985711, 2023).
cancer (3 papers, 2021 to 2025). A tumor composed of atypical neoplastic, often pleomorphic cells that invade other tissues. "The TCGA Pan-Cancer cohort showed six genes [METTL1, METTL11B, EEF1AKNMT, METTL18, EEF1AKMT3 (METTL21B), RRNAD1 (METTL25B)] with high-level amplifications above 2%." (PMID 34285249, 2021).
EEF1AKMT3 also shares sentences with these, for which no sentence is quoted: colorectal cancer (2 papers); multiple sclerosis (2); autoimmune thyroid disease (1); glioma (1); infection (1); measles (1); sarcoidosis (1).